HIF1A (hypoxia inducible factor 1 subunit alpha)
Diseases named in the same sentence as HIF1A in open-access papers (continued):
Sharing a sentence is not in itself a finding about the gene and the disease.
breast cancer (continued). "It suppressed the expression levels of HIF-1α and VEGF in breast cancer cells in vitro and in vivo, and induced the expression of apoptosis-related proteins in breast cancer xenografts." (PMID 35805939, 2022). "Although the HIF-1α is the leading isoform in breast cancer, the HIF-2α isoform is a critical regulator of physiological and pathophysiological angiogenesis and, at least, similarly important to HIF-1α." (PMID 36139678, 2022). "HIF-1α protein can directly activate JFK transcription, which in turn leads to HIF-1α-induced glycolysis and make hypoxic breast cancer cells insensitive to chemo-radiotherapeutic treatment." (PMID 36226050, 2022). "HIF-1α promotes EMT and invasion via activation of the TGF-ß-SMAD3 pathway in breast cancer patients, the Wnt/ß-catenin pathway in hepatocellular carcinoma and prostate cancer, and hedgehog signaling in pancreatic cancer cells." (PMID 35372069, 2022). "The degradation of HIF-1α accelerates the reversal of the expression of glycolysis-related proteins GLUT1, PDK1, and HK2 in cancer cells, which weakens the glycolysis of breast cancer cells and indirectly leads to tumor growth inhibition." (PMID 35350760, 2022). "In metastatic melanoma and breast cancer samples, a significantly high positive correlation was observed between KDM6B and HIF1α mRNA (R = 0.45, p-value = 0.018; R = 0.26, p-value = 0.0014)." (PMID 35186918, 2022). "Consistent with our findings, ALKBH5 has been reported to positively regulate Nanog stability and expression in response to hypoxia-inducible factor (HIF)-1α and HIF-2α in breast cancer stem cells (BCSCs)." (PMID 35552718, 2022). "Inhibition of HIF-1α, P4HA1, or P4HA2 via short hairpin RNAs has been shown to decrease collagen deposition in breast cancer cells and fibroblasts in vitro." (PMID 36140753, 2022). "In breast cancer, ZMYND8 was found to interact with HIF-1α and HIF-2α, and it can also recruit of BRD4 and release paused RNA polymerase II to enhance the HIF-induced oncogenicity." (PMID 34834420, 2021). "Because HIF1A is a regulator of CD44 and increases CD44 expression, hypoxic region in breast cancer has also been reported to contain cells with a higher concentration of CD44 expression." (PMID 35187044, 2021). "In order to study the expression of HIF-1α, GLUT1 and CAIX genes in liquid biopsy of patients with breast cancer, samples from 125 patients and 25 healthy donors were evaluated." (PMID 33888756, 2021). "Down-regulation of MiR-20b can activate HIF-1α and VEGFA to promote breast cancer migration and invasion." (PMID 34857023, 2021). "EGC reduced LDHA activity in breast cancer (MCF-7 and MDA-MB-231) cell lines; notably, LDHA inhibition results from the dissociation of HSP90 from HIF-1α, resulting in HIF-1α proteasomal degradation." (PMID 33401572, 2021). "In support of our clinical findings that TARBP2 is correlated with tumor hypoxia, our IHC staining showed the positive correlation between HIF-1α and TARBP2 in human breast cancer tissues." (PMID 35008634, 2021). "CBD inhibits Src activity, which decreases HIF-1α through the degradation of VHL recruitment and the direct reduction of HIF-1α protein synthesis in mammospheres as well as breast cancer cells." (PMID 34830821, 2021). "This study focused on the impact of HIF1α on predicting response and survival of taxane-based neoadjuvant therapy (NAT) for breast cancer (BC) patients and the concrete mechanism that HIF1α mediated paclitaxel chemo-insensitivity." (PMID 34595177, 2021). "Tissue lactate is closely related to hypoxia and we have shown previously a correlation between HIF1A expression and LAC/PYR in a varied group of treatment-naïve breast cancers." (PMID 34625424, 2021). "Clarifying these points should deepen our understanding of the roles of hypoxia generally, and JFK and HIF-1α/HIF-2α specifically, in breast cancer." (PMID 34336836, 2021).
breast cancer (continued). "In breast cancer, pomolic acid was discerned to abolish the stimulatory effect of EGF on HIF-1α and VEGF expression." (PMID 34575983, 2021). "We have also shown that in breast cancer LAC/PYR correlates with both the expression of MCT1, which is responsible for the cellular uptake of pyruvate, and hypoxia as measured from HIF1α expression." (PMID 34625424, 2021). "We find that JFK is inducible under hypoxic conditions, in which hypoxia-inducible factor HIF-1α binds to and transcriptionally activates JFK in breast cancer cells." (PMID 34336836, 2021). "Further analysis revealed that the expression of HIF-1α, along with VCAM-1 and P65 levels, correlated well with each other in breast cancer and TNBC tissues, and was in accordance with previous studies." (PMID 33708767, 2021). "Although we focused on angiogenesis related to HIF-1α in CBD treatment in our study, we demonstrated that CBD inhibits the proliferation, migration, and invasion of breast cancer cells." (PMID 34830821, 2021). "Metformin exerted an anti-angiogenic effect in breast cancer models by inhibitiHER2-mediated VEGF upregulation and HIF-1α-mediated VEGF up-regulation, suggesting a novel mechanism of metformin targeting the HER2/HIF-1α/VEGF signaling axis." (PMID 34778378, 2021). "Plk1 expression correlated with HIF-2 targets in ccRCC and in testicular adenocarcinoma, with HIF-1α and HIF-2α targets in 6 out of 26 cancer types like breast cancer, liver cancer, and sarcoma." (PMID 33547392, 2021). "Deguelin reduced the expression of HIF-1α in lung cancer (H1299), human squamous cell carcinoma (UMSCC38), prostate cancer (PC3), gastric cancer (MKN-45), and breast cancer (MCF-7) cell lines, as well as in vascular endothelial cells." (PMID 33401572, 2021). "Regorafenib was demonstrated to possibly exhibit antitumor activity on a breast cancer cell line via, at least in part, modulation of the P2X7/HIF-1α/VEGF, P2X7/P38, P2X7/ERK/NF-κB, and P2X7/beclin 1 signaling pathways." (PMID 34940128, 2021). "A series of molecules such as hypoxia induced HIF-1α, TGF-β, and NOTCH1 have been reported to promote CSC transdifferentiate to endothelial cells or pericytes in glioblastoma, breast cancer, and renal carcinomas." (PMID 33946480, 2021). "Analyses using the CellMiner tool and the Kaplan–Meier plotter database showed that HIF‐1α expression was inversely correlated with TAM therapeutic response in NCI‐60 cancer cells and breast cancer patients." (PMID 34841716, 2021). "We also analyzed public data to evaluate the HIF-1α and JFK mRNA expression levels in breast cancers." (PMID 34336836, 2021). "Taken together, these findings suggest that HIF-1α-induced UCA1 overexpression is involved in the promotion of cell viability and inhibition of apoptosis in hypoxic breast cancer cells." (PMID 34054950, 2021). "The study demonstrated that miR-7641 decreased breast cancer cell glycolysis by HK2, GLUT1, LDHA which regulated by HIF-1α." (PMID 34238918, 2021). "At the same time, hypoxia can induce MiR-153 to fine-tune HIF1α/VEGFA in breast cancer angiogenesis, MiR-100 can inhibit in vitro angiogenesis by regulating the mTOR/HIF-1α/VEGF signal transduction axis in breast cancer cells." (PMID 34857023, 2021). "APG inhibited the expression of HIF-1α and mediated cell death through the suppression of STAT3 under hypoxia in breast cancer cells, suggesting that APG is a powerful anti-cancer drug to overcome hypoxia-induced chemoresistance." (PMID 34948250, 2021). "Expression of HIF-1α and GLUT1 in the blood of breast cancer patients is significantly higher (90–91 and 160–161 fold increased expression, respectively; p < 0.0001) than that found in healthy women." (PMID 33888756, 2021).
breast cancer (continued). "An antisense lncRNA of HIF-1α (ENST00000554254.1), which we named HIFAL (HIF Antisense LncRNA), was most prominently upregulated in the hypoxic cells and in breast cancer tissues." (PMID 33637716, 2021). "It has been confirmed that increased HIF‐1α expression and activity are involved in TAM resistance in breast cancer cells." (PMID 34841716, 2021). "In breast cancer, ALKBH5 is a direct target of hypoxia-inducible factor 1α (HIF-1α) and HIF-2α and regulates breast cancer stem cell phenotype by downregulating the m6A modification on Nanog mRNA methylation." (PMID 33428593, 2021). "Collectively, our data suggest that VCAN-AS1 is upregulated in breast cancer and promotes its progression by regulating the miR-106a-5p-mediated STAT3/HIF-1α pathway." (PMID 34365889, 2021). "The expression of HIF-1α was very low in MCF-10A cells, and the level of expression increased as the degree of malignancy of the breast cancer cells increased." (PMID 34253828, 2021). "A combination of curcumin and glucose gold nanoparticles induces apoptosis in CSCs and reduces expression levels of hypoxia inducible factor-1α (HIF-1α) and HSP90 in sensitizing breast cancer cells to radiotherapy." (PMID 34769099, 2021). "In breast cancer, HIF-1α-stabilizing long noncoding RNA (HISLA) was proved to prevent the inactivation of HIF-1α from hydroxylation by prolyl hydroxylase domain 2 (PHD2)." (PMID 34717710, 2021). "Peptides that derive from HIF-1α C-TAD (aa 766–826 and aa 786–826) or p300 CH1 peptides reduced EPO promoter activity when overexpressed in HCT-116 colon and MDA-MB435 breast carcinoma cell lines." (PMID 33499237, 2021). "Cell proliferation of H1299, A549 (NSCLC), MCF7, MDAMB231 (Breast cancer), MKN1, MKN45 (Gastric cancer), and U87MG, SHSY5Y (Brain cancer) cells was dependent on HIF-1α, and HCC cell proliferation was dependent on HIF-2α under hypoxia." (PMID 32847073, 2020). "On the other hand, Kong and colleagues demonstrated the pivotal role of miR-155 in tumor angiogenesis of breast cancer tissue through targeting VHL and subsequent HIF-1α stabilization." (PMID 32806571, 2020). "In in vitro experiments, hypoxia induced the expression of HIF-1α and Nur77 in breast cancer cells, while LNT addition down-regulated HIF-1α expression in an oxygen-free environment, and this process was in a manner of Nur77 dependent." (PMID 33245358, 2020). "Interestingly, in this context, the loss of CAV1 expression in breast cancer tumor–stroma reportedly induces HIF1α activation and the loss of CAV1 in stromal cells leads to a glycolytic and catabolic phenotype through HIF1α stabilization, favoring synergy with oxidative breast cancer cells." (PMID 32825247, 2020). "In breast cancer, upregulated P4HA1 was crucial for HIF-1α stabilization, cancer metastasis, and chemoresistance." (PMID 33299876, 2020). "In breast cancer cells, acute hypoxia increased HIF-1α expression, while chronic hypoxia continuously enhanced HIF-2α expression and induced the resistance of breast cancer cells to chemotherapy." (PMID 32024881, 2020). "ALKBH5 belongs to the non-heme Fe(ii)- and α-ketoglutarate (KG)-dependent dioxygenase AlkB family of proteins demethylated NANOG mRNA, and stimulated the expressions of HIF-1α and HIF-2α of breast cancer cells when exposure to hypoxia." (PMID 32500031, 2020). "Specifically, YB1 translationally activates HIF1α expression to promote sarcoma metastasis and activates Snail1 and other transcription factors to induce EMT in breast cancer." (PMID 32814829, 2020). "In a recent study involving breast cancer cells MCF-7 and MDA-MB-435, rhein was reported to play an important role in reducing tumor growth and vasculogenesis by inhibiting the expression of HIF-1α." (PMID 32408623, 2020). "Expression of GLUT1 can also be regulated through hypoxia response elements by hypoxia-inducible factor (HIF)-1a whose expression is correlated with BRCA1 and basal phenotypes in breast cancer such as those observed in TNBC." (PMID 33324565, 2020).
breast cancer (continued). "For example, HIF1a leads to the upregulation of PDK1, which accelerates glycolysis and plays a critical role in promoting stem-cell traits of breast cancer stem cells." (PMID 32642002, 2020). "In breast cancer cell lines, UCA1 upregulation is induced by tamoxifen treatment in a HIF-1α dependent manner." (PMID 32640630, 2020). "Rhein was also shown to inhibit NF-κB activation and its downstream targets HIF-1α and VEGF165 in breast cancer cells, MCF-7 and MDA-MB-435." (PMID 32408623, 2020). "In breast cancer cells, TRAF6 overexpression correlated with increased HIF-1α signaling and metastasis." (PMID 33142239, 2020). "Four human cancer cell lines, DLD-1 (colon cancer), SNB-75 (glioblastoma), Hs 578 T (breast cancer), and MDA MB 231 (breast cancer) were treated with an RSK inhibitor (SL0101), ABCB1 inhibitor (zosuquidar), or HIF-1α inhibitor." (PMID 33335181, 2020). "In contrast to HIF-1α, Spalt-like transcription factor 2 (SALL2), a transcription factor related to disease progression, enhances the sensitivity of breast cancer cells to tamoxifen, while ERα is downregulated after silencing SALL2." (PMID 33362547, 2020). "STAT3 signaling pathway plays a crucial role in proliferation (Bcl-2, Survivin), angiogenesis (HIF1α, VEGF), and epithelial-mesenchymal transition (Vimentin, MMP-9) in breast cancer cells and has been validated as a drug target for cancer therapy." (PMID 31948057, 2020). "MYC and MCL1, which are frequently co-overexpressed in breast cancer stem cells (BCSC) of TNBC, act as enhancers of mitochondrial OXPHOS and synergistically upregulate HIF-1α expression." (PMID 32296646, 2020). "The aim is to investigate the mechanism of HIF‐1α and signal transducer and activator of transcription‐3 (STAT3) interaction and discover a compound to disrupt the interaction in breast cancer cells." (PMID 32065498, 2020). "In breast cancer, PML regulates aggressiveness and metastatic features through the control of the stem cell gene, SOX9, and the Hypoxia-inducible factor 1 alpha (HIF1α) signaling." (PMID 31570853, 2020). "We then examined gene expression from 9 different breast cancer datasets and found correlation between HIF1A and LOX, ITGA5, and FN1 mRNAs, supporting the upstream regulatory role of HIF1A in their transcription." (PMID 32415208, 2020). "LOX is known as an enzyme that crosslinks extracellular matrix proteins such as collagen and promotes breast cancer metastasis, and the release of LOX is regulated by HIF-1α." (PMID 33126606, 2020). "This process reduced SENP1 expression and prevented the deSUMOylation of HIF-1α, ultimately leading to HIF-1α degradation and breast cancer metastasis suppression." (PMID 32093760, 2020). "Previous work on the crucial role of SOX2 in breast cancer cell migration showed that SOX2 upregulation in hypoxic conditions facilitated NEDD9 transcription and subsequent activation of HIF-1α expression." (PMID 32913192, 2020). "LCN2 is reported to induce the production of HIF-1α and VEGF in breast cancer cells to stimulate angiogenesis, via the ERK signaling pathway." (PMID 33123472, 2020). "Consistently, another previous study came to similar conclusions in breast cancer, showing that primary tumours that induce bone micrometastases have specific molecular signatures, which include the rat sarcoma (RAS) family and HIF-1α." (PMID 32527062, 2020). "Overexpression of HIF-1α in 293T cells caused a 2-3 fold increase in BHLHE40 transcription, while BHLHE40 expression was shown to correlate with hypoxia and angiogenic markers such as HIF1α, angiogenin and VEGFD in breast cancer tissue." (PMID 32577154, 2020). "Our previous study also reported that the expression of HIF-1α, leading to the secretion of lysyl oxidase (LOX), is increased in the highly metastatic breast cancer cells MDA-MB-231." (PMID 33126606, 2020).
breast cancer (continued). "To establish a link between miRNA, HIF-1α, and the COX-2/EP4/PI3K/Akt pathway, we measured NFκB1, COX-2, EP4, and VEGFA gene expression in breast cancer cell lines, in both normoxia and hypoxia." (PMID 32707933, 2020). "In breast cancer cells, SNAT2 can be induced by both HIF-1α and estrogen receptor-α (ER-α), the binding sites for both HIF-1α and ER-α being overlapped in cis-regulatory elements of the SNAT2 gene." (PMID 32252351, 2020). "Given that HIF‐1α and Kindlin‐2 are overexpressed in breast cancer, we aimed to determine the roles of HIF‐1α and Kindlin‐2 in breast cancer; we detected the expression levels of HIF‐1α and Kindlin‐2 in MCF7 cells under hypoxic conditions." (PMID 32436609, 2020). "LincRNA-p21 is inducible by hypoxia or HIF1α function in breast cancer cells, and binds to HIF1α and its E3 ubiquitin ligase von Hippel-Lindau (VHL), thereby disrupting the VHL-HIF1α interaction." (PMID 33123488, 2020). "The baseline level of HIF1α in untreated control MCF10A cells (40 ± 4.34 pg/ml), was much lower than that in both ER +ve (300 ± 32.03 pg/ml) or ER−ve (1000 ± 59.21 pg/ml) breast cancer cells." (PMID 31980706, 2020). "Extracellular fatty acid influx and lipid droplet accumulation are enhanced via HIF-1α-mediated induction of fatty acid binding protein 3 and 7 (FABP3 and FABP7), while de novo lipogenesis is repressed in glioblastoma and breast cancer cells under hypoxia." (PMID 32389123, 2020). "In tumor tissues, we also recorded a strong correlation between miR526b and HIF-1α and between miR655 and HIF-1α, which suggests that HIF-1α and miRNAs strongly interact to enhance breast cancer progression." (PMID 32707933, 2020). "Collectively, our results demonstrate that activation of the ERK/HIF-1α/EMT pathway is involved in the XCL1-induced migration of both MDA-MB-231 and SK-BR-3 breast cancer cells." (PMID 33374849, 2020). "Notch target genes including HES1 and HEY1 were increased by hypoxia and both HIF-1α and HIF-2α synergized with the Notch co-activator MAML1 in promoting Notch activity among breast cancer cells." (PMID 32322559, 2020). "This interferes with PHD2-mediated HIF-1α hydroxylation and subsequent degradation, resulting in increased HIF-1α levels and enhanced chemoresistance as well as glycolysis in breast cancer." (PMID 32640630, 2020). "We tested two predicted OCN pairs in each cancer type, including NCSTN and DNM1, and NCSTN and OGT in liver cancer; CCNA2 and PTP4A1, and HIF1A and PARP1 in lung cancer; and CCNA2 and PTP4A1, and PLK1 and PTP4A1 in breast cancer." (PMID 31097707, 2019). "The expression levels of β2M, HIF-1α, p-CREB, VEGF, p-SGK1, p-ERK1/2, and Bcl-2 were significantly higher in cancer tissues of patients with luminal A breast cancer compared to adjacent tissues (p < 0.05)." (PMID 30866857, 2019). "Collectively, we first determined the synergistic anti‐cancer effects of PD and 2‐DG coutreatment and found that the effect was mediated by the ROS/PI3K/AKT/HIF1α/HK2 and glycolysis pathways in breast cancer." (PMID 30920152, 2019). "Collectively, these data indicate that HIF-1α expression and activity decreased in MCF-7 breast cancer cells." (PMID 30940798, 2019). "The human breast cancer cell line, MDA-MB-231, overexpresses HIF-1α and constitutively secretes Hsp90α2,6,36." (PMID 31641193, 2019). "Conversely, increased levels of HIF-1α expression and activity were observed in MDA-MB-231 cells or HER2 + breast cancer cells." (PMID 30940798, 2019). "Furthermore, these non-CpG sites are strongly associated with H3K9ac, which may establish a tissue-specific epigenetic modification pattern for HIF-1α gene transcriptional regulation, pointing to new directions for future understanding of this epigenetic modification in breast cancer therapy." (PMID 30940798, 2019). "Nrf2‐dependent G6PD/HIF‐1α activation provokes Notch1 signalling by up‐regulation of Jagged1 and Hes1, thereby promoting EMT in breast cancer cells." (PMID 30809937, 2019).